LAG3 (lymphocyte activating 3)
Diseases named in the same sentence as LAG3 in open-access papers (continued):
Sharing a sentence is not in itself a finding about the gene and the disease.
tumor (continued). "As a new-generation immune checkpoint, LAG3 is expected to become a promising target in tumor immune therapy." (PMID 37600786, 2023). "FGL1 is a novel ligand of LAG3 that results in T-cell depletion and subsequent dysfunction, as well as tumor cell escape from immune surveillance." (PMID 38139416, 2023). "Apart from activated T cells and Tregs, LAG-3 is mostly expressed on tumor-infiltrating lymphocytes (TILs) and NK cells." (PMID 36672492, 2023). "The mIHC/IF analysis of HCC tissue samples confirmed the expression of LAG-3 within the tumor microenvironment." (PMID 37342338, 2023). "In a study on oropharyngeal squamous cell carcinoma (OPSCC) including 241 tumor tissues aiming to describe the expression of LAG-3, Tim-3, and VISTA in the TME of OPSCC, immunohistochemistry showed that 168 OPSCC samples stained positive for VISTA." (PMID 36960057, 2023). "The multivariate analysis regarded LAG-3 expression (HR = 1.86; 95% CI, 1.00 − 3.44, P = 0.049) and residual tumor (HR = 9.71; 95% CI, 5.13 to 18.52, P < 0.001) as independent prognostic factors." (PMID 37179337, 2023). "Along with being a prognostic marker, the role of LAG-3 in the tumor metastasis makes it a good therapeutic target for the treatment of cancer." (PMID 37345111, 2023). "In both Cxcr3+/+ and Cxcr3−/− mice, tumor-infiltrating T cells upregulated PD-1 and Lag3 and lost Klrg1 as compared to splenic tetramer + T cells." (PMID 36472588, 2023). "LAG3 expression was also found to be associated with microsatellite instability (MSI), copy number variation (CNV), simple nucleoside variation (SNV), tumor mutation burden (TMB), and neoantigen in various types of cancers." (PMID 38041068, 2023). "Of the two groups, much less tumor resolution occurred (0–40%) in the mice treated with anti-PD-1 or anti-LAG-3 blockade." (PMID 37999131, 2023). "LAG-3 can also be stimulated by soluble actors (e.g., galectin-3) secreted by apoptotic tumor cells." (PMID 37444609, 2023). "Our results generally showed that CD45RO + lymphocytes, followed by CD3 + lymphocytes, were the most frequent subsets in both areas of CRC tumor tissues, while LAG3 + cells showed the lowest frequency." (PMID 36765348, 2023). "Similar to LAG-3, the blockade of Tim-3 targets can enhance the function of effector T cells, promote cytokine release, and inhibit tumour progression." (PMID 37426674, 2023). "For instance, markers of both leukocyte activation (CD44) and exhaustion (LAG3) were also highest in the Brca1-null tumours." (PMID 38017453, 2023). "The percentages of LAG-3+ sTILs, LAG-3 + iTILs, PD-L1+ immune cells (IC) and PD-L1+ tumor cells (TC) were 55.1%, 40.8%, 69.4% and 14.3%, respectively." (PMID 36945923, 2023). "Collectively, these studies identify a pivotal role for LAG-3 in dampening anti-tumour immunity and highlight that LAG-3 blockade can induce durable responses in pre-clinical models." (PMID 36445478, 2023). "Consistent with the greater immunogenicity of MMRd tumors, MMRd T cells were enriched in programs involving cytotoxicity (granulysin, granzyme B, perforin) and exhaustion (PD-1, TOX, LAG3), suggesting chronic stimulation of tumor-reactive T cells." (PMID 37492581, 2023). "In tumors, LAG-3 is expressed by exhausted CD8+/PD-1+ tumor-infiltrating lymphocytes, but its role in immune escape is still controversial." (PMID 37371818, 2023). "This feature makes the LAG3 protein an attractive marker for the assessment of potential anti-tumor response and, thus, patient stratification for immunotherapy." (PMID 37311986, 2023). "Tumor cells can also evade immune surveillance through manipulation of the IC, LAG-3, which acts as a negative regulator of tumor infiltrating lymphocytes (TILs)." (PMID 37345111, 2023). "Tumor-infiltrating lymphocytes can overexpress LAG-3, which contributes to their dysfunction and immune exhaustion." (PMID 37427115, 2023).
tumor (continued). "We then classified patients based on their primary tumor location into two groups: left/rectum- and right- sided tumors, and repeated the analyses in patients with high and low scores of LAG3 and CD45RO." (PMID 36765348, 2023). "Based on several algorithms from TIMER2.0 database, we investigated the correlation between tumor-infiltrating immune cells and LAG3 expression across various cancer types." (PMID 38115039, 2023). "We utilized the TIMER2.0 platform to investigate the expression profiles of LAG3 in tumor tissue and normal tissue derived from TCGA datasets, thereby revealing distinct patterns of LAG3 expression across various cancer types." (PMID 38115039, 2023). "The binding of LAG-3 and its ligands increase intratumoral T cells, the inhibition of CD4pos T cell activation and CD8pos T cell cytotoxic functions, and tumor cell evasion of apoptosis." (PMID 37046702, 2023). "PDCD-1 and LAG3, two immunosuppressive molecules, play important roles in tumor-cell-mediated immune escape." (PMID 37131179, 2023). "The relationship between the expression levels of CD274, TIGIT, PDCD1, CTLA4 and LAG3 in tumor tissues of normal and LUAD patients and the relationship between each gene and the survival rate of LUAD patients." (PMID 36959799, 2023). "Other studies also confirmed the regulatory roles of highly expressed LAG3 in the tumor infiltration of immune cells, including T cells, B cells, NK cells and DCs." (PMID 38115039, 2023). "Combination PD-1/CTLA-4 blockade increased the proliferation and infiltration of CD4+ and CD8+ T-cells more than PD-1 blockade alone, and significantly decreased the percentage of tumor infiltrating exhausted LAG3+ TIM3+ CD8+ T cells compared to either alone." (PMID 37449205, 2023). "Beyond PD-1/PD-L1 and CTLA-4, LAG-3 has emerged as a novel tumor immunotherapy target as an indication of tumor prognosis." (PMID 37803407, 2023). "LAG-3 mRNA expression was increased in tumor-infiltrating CD8+ T cells from HBV-related HCC patients compared to controls which was associated with lower capacity to produce IFN-γ." (PMID 37056774, 2023). "LAG3 was confirmed to be highly expressed in tumor-infiltrating NK cells, Tregs, and B cell subsets in addition to CD8+ T cells, reflecting our data from PB." (PMID 36719749, 2023). "Another preclinical study examined mechanisms of enhanced anti-tumor immunity with a dual blockade of LAG-3 and PD-1 in an ovarian tumor murine model." (PMID 37999131, 2023). "As expected, subsequent combination therapy with HPV mRNA-LNP vaccination and immune checkpoint blockade (anti-LAG3/anti-CTLA4) further promoted tumor regression." (PMID 37773254, 2023). "LAG-3 staining of lymphocytes was observed in 43 baseline tumor specimens (81%, n = 43/53) of patients treated with combination anti-LAG-3 + anti-PD-1 ± anti-CTLA-4 immunotherapy." (PMID 37808404, 2023). "We evaluated LAG-3 expression in tumor-infiltrating lymphocytes (TILs) via immunohistochemical analysis using tissue microarrays containing surgically resected specimens from 171 patients with OCCC." (PMID 37179337, 2023). "The positive expression of LAG-3 in tumor TIIs was a prognostic factor for disease recurrence in patients, and patients with positive expression of LAG-3 in TIIs had a poorer DFS (p = 0.026)." (PMID 36875956, 2023). "Tumor-infiltrating Tregs express high levels of cell surface molecules associated with T-cell activation, such as CTLA4, PD-1, LAG3, TIGIT, ICOS, and TNF receptor superfamily members including 4-1BB, OX40, and GITR." (PMID 37182149, 2023). "Although the role of LAG3 expression in tumor prognosis, including MPM, is limited, some studies suggest that LAG3 expression was correlated with the prognosis of patients with MPM." (PMID 38062416, 2023). "We and others have previously shown that therapeutic co-targeting of PD-L1 and LAG-3/ICOS enhances the tumor growth inhibition of either antibody used in monotherapy." (PMID 36997666, 2023).
tumor (continued). "Our results showed that tumor targeting-related immune checkpoint genes such as CD274 (p = 0.0137), TGFB1 (p = 0.0175), PDCD1 (p < 0.001), CTLA4 (p < 0.001), and LAG3 (p < 0.001) were significantly associated with APOC1." (PMID 36969562, 2023). "It has been shown to be frequently co-expressed with PD-1, whereby high LAG-3 expression is found primarily in tumor-infiltrating T cells." (PMID 37004702, 2023). "Our experimental results showed that the intensity of red fluorescence was significantly reduced in A549 cells after si-LAG3 treatment, suggesting that downregulating LAG3 expression in LUAD A549 cells will inhibit tumor cell proliferation." (PMID 37781711, 2023). "LAG-3 and PD-L1 was evaluated in tumor-infiltrating lymphocytes (TILs) using immunohistochemistry (IHC)." (PMID 36945923, 2023). "T cells in the TME, which are called tumor-infiltrating lymphocytes, overexpress LAG-3, leading to cell dysfunction, exhaustion of the immune system, and advantageous conditions for tumor proliferation." (PMID 37047684, 2023). "In summary, we conducted a detailed pan-tumor expression profiling study of immune cells that express LAG-3 and its ligands." (PMID 37795090, 2023). "In TIGIT+ Treg cells, the expression level of many immunosuppressing marker genes, including Foxp3, Helios, neuropilin-1, CTLA-4, PD-1 and LAG-3, was upregulated, which inhibited the tumor killing function of T cells." (PMID 38110467, 2023). "An increased expression of LAG-3 on the surface of tumor-infiltrating CD8+ T cells also correlated with advanced stage disease in OAC patients." (PMID 37520544, 2023). "LAG-3high Tregs secrete immunosuppressive cytokines, and blockade of LAG-3 signaling using an anti-LAG-3 antibody slows tumor growth." (PMID 37907742, 2023). "LAG-3 upregulation, which is observed in tumor-infiltrating lymphocytes in the majority of patients with HCC, is a mechanism of immune escape by tumors." (PMID 37342338, 2023). "Neoadjuvant anti-LAG-3/anti-PD-1 treatment mediated tumor infiltration by memory CD4+ and effector CD8+ T cells in the post-treatment tumor specimens of patients with favorable treatment response." (PMID 36674809, 2023). "Meanwhile, the expression of LAG3 and TIGIT in this group is relatively high, combined with higher tumor mutation burden (TMB) and microsatellite instability (MSI), which suggests a better response to immune checkpoint inhibitors." (PMID 35801342, 2023). "CD137 is also a costimulatory molecule expressed on activated T-cells within tumours, along with the immune checkpoints LAG3, TIM3 and TIGIT." (PMID 37013636, 2023). "DNAM-1LO CD8+ T cells accumulate at the tumour site and upon interaction with cognate antigen exhibit an exhausted phenotype, expressing high levels of PD-1, LAG-3, TIM-3, and TIGIT." (PMID 37325585, 2023). "Given the fact that PDL1 is routinely upregulated in tumor cells, the triple combo medicine γδ T cell, anti-LAG3 mAb, and anti-PD1 or anti-PDL1 mAb should be a better choice." (PMID 37989744, 2023). "LAG-3 expression contributes to the immune escape mechanism of tumors and is often observed in tumor-infiltrating lymphocytes during cancer progression." (PMID 37444609, 2023). "LAG3 inhibitor monotherapy resulted in fewer reductions in tumor proliferation than did PD-1 inhibitor monotherapy in an in vivo study." (PMID 38062416, 2023). "LAG3 was expressed more commonly by CD3+/CD8+ T cells in the tumor area than in the stromal compartment." (PMID 37311986, 2023). "Increased micro-environmental cell LAG-3 expression in SMM contributed to the suppression of anti-tumor T-cell responses and the increased progression to symptomatic MM." (PMID 38203720, 2023). "HAVCR2 and LAG3 can work synergistically to promote the exhaustion of effector T cells and inhibit anti-tumor function." (PMID 38239349, 2023).
tumor (continued). "Taken together, these pre-clinical and clinical studies investigating A2aR and LAG-3 demonstrate that targeting these novel ICs to enhance anti-tumour immunity is a viable strategy for boosting the efficacy of conventional PD-1 ICBs." (PMID 36445478, 2023). "Taken together, LAG-3 co-targeting can be reasonably employed to augment anti-tumor immunity in combinational ICI treatment." (PMID 37345056, 2023). "As LAG-3 binds to HLA class II, we analyzed a possible role of tumor cells in the immune suppressive TME, and interestingly, found that the expression of LAG-3 and that of HLA-DR are significantly correlated in GBM." (PMID 37936683, 2023). "The correlation between LAG3 and these gene markers in TIICs indicates that LAG3 regulates the tumor immune system in MPM." (PMID 38062416, 2023). "LAG3 + TILs in IM were also increased in tumor tissues with higher T-stages in the entire cohort (P = 0.027)." (PMID 36765348, 2023). "Since the functional state of TILs is linked to their potential anti-tumor activity, we analyzed the expression of selected activation markers (HLA-DR and CD103) and inhibitory markers (PD-1, TIM-3, and LAG-3)." (PMID 37532709, 2023). "More importantly, LAG-3 and PD-1 can synergistically exert more intense immunosuppression on the tumor microenvironment (TME) immune cells." (PMID 37264298, 2023). "Highly correlated with LAG3, adoptive cell therapy using tumor-infiltrating lymphocytes (TILs) was a promising immunotherapy approach for COAD." (PMID 36949947, 2023). "LAG3 expression was detected immunohistochemically in the membrane of tumor-infiltrating lymphocytes and on tumor-infiltrating CD4 or CD8 cells in MPM." (PMID 38062416, 2023). "Programmed death-1 (PDCD-1) and lymphocyte activating 3 (LAG3), two important immunosuppressive molecules, play crucial roles in immune escape of tumor cells." (PMID 37131179, 2023). "Subgroup analysis based on tumor type indicated that higher expression of LAG3 was correlated with worse PFS in patients with BLCA (HR = 1.58, 95% CI 1.12–2.23, P = 0.010) and SARC (HR = 1.10, 95% CI 1.02–1.19, P = 0.016)." (PMID 38041068, 2023). "Dual blockade of PD-1 and LAG3 has led to decreased tumor growth and enhanced anti-tumor immunity in mouse models." (PMID 37311986, 2023). "LAG3 is strongly upregulated upon continuous T cell stimulation due to persistent exposure to tumor antigens." (PMID 37311986, 2023). "Collectively, these findings exhibited strongly supported the tumor-suppressive roles of LAG3 in SKCM." (PMID 38115039, 2023). "Though further research is required to understand the functions of LAG-3, gene-editing provides a potential mechanism for enhancing lymphocyte recognition of tumor cells." (PMID 37064017, 2023). "Analysis of tumor-infiltrating lymphocytes in HCC revealed that LAG-3 expression was upregulated in HBV-specific CD8+ T cells compared to the CD8+ T cells in the peripheral blood." (PMID 37999131, 2023). "Multivariate analysis revealed LAG-3 expression (hazard ratio [HR] = 1.86; 95% confidence interval [CI], 1.00 − 3.44, P = 0.049) and residual tumor (HR = 9.71; 95% CI, 5.13 − 18.52, P < 0.001) as independent prognostic factors." (PMID 37179337, 2023). "LAG3 was first reported in 1990 and is an important immune checkpoint expressed on the membranes of tumor-infiltrating lymphocytes." (PMID 38062416, 2023). "The correlation between LAG3 expression and mRNA expression of tumor immune infiltration cells (TIICs) gene markers in MPM is indefinite." (PMID 38062416, 2023). "We used 86 MPM cases from TCGA and 38 MPM cases from our cohort to analyze the expression of LAG3 in tumor-infiltrating lymphocytes." (PMID 38062416, 2023). "During chronic infections and tumor stimulation of the immune system, T cells exhibit elevated LAG-3 expression on their surface and their proliferation and cytokine production are decreased, ultimately resulting in T cell failure." (PMID 37841254, 2023).
tumor (continued). "These ligands are present on diverse cell types within the tumor microenvironment (TME), and their interaction with LAG-3 can facilitate tumor immune evasion by dampening anti-cancer immune responses." (PMID 37504358, 2023). "Dual blockade of the FGL1/LAG-3 and PD-1/PD-L1 signaling pathways greatly improved the T-cell killing ability of tumor cells." (PMID 38106403, 2023). "LAG-3 blockade stimulates immune activation against tumor cells and enhances the effect of other immune checkpoint inhibitors." (PMID 37427115, 2023). "Chronic stimulation of T cells by tumor antigens leads to a process of lymphocyte exhaustion, accompanied by increased surface LAG3 and PD1 levels." (PMID 36900156, 2023). "This subset also expressed higher CTLA-4 (both in the periphery and NT) and LAG-3 (at the tumor site) than the CD28− counterpart." (PMID 37898752, 2023). "Preclinical data showed strong synergy between PD-1 and LAG-3 inhibitory pathways against tumor antigens and blockade of these checkpoints improved anti-tumor CD8 T cells responses." (PMID 37079257, 2023). "The correlation of LAG3 expression and mRNA expression of tumor immune infiltration cells (TIICs) gene markers were estimated using Spearman correlation." (PMID 38062416, 2023). "Lymphocyte activation gene 3 (LAG3) is thought to contribute to T cell exhaustion within the tumor microenvironment of solid tumors." (PMID 37311986, 2023). "The positive expression of LAG-3 in tumor TIIs was a prognostic factor for disease recurrence, and patients with positive expression of LAG-3 in the TIIs had poorer disease-free survival (p = 0.026)." (PMID 36875956, 2023). "Soluble LAG-3 fusion protein enhances the capacity of MHC-II macrophages or immature dendritic cells to induce T-cell responses whereby tumor regression involves the recruitment of CD8+ T-cell response." (PMID 37484526, 2023). "The BTC tumor edge serves as the primary location for active infiltration by FOXP3+CD4+ Tregs that express elevated levels of lymphocyte activation gene 3 (LAG-3) and T cell immunoglobulin and mucin domain-containing protein 3 (TIM3)." (PMID 38213535, 2023). "In eight of the 13 tumor types analyzed, high LAG-3 expression (as defined by >15 LAG-3+ tumor-infiltrating lymphocytes (TILs)) was found in ≥30% of the samples, with DLBCL having the highest LAG-3 expression." (PMID 37857711, 2023). "The marker profiles of both CD8 TCM and TEM cells that co-expressed both PD-1 and LAG-3 exhibited generally robust signal intensities for several activation, stimulatory, and inhibitory markers, which was observed across differing tumor types." (PMID 37795090, 2023). "The role of LAG-3 in murine NK cells was originally described using knock-out mice and appeared as a promoter of NK cell cytotoxicity against certain tumor cell lines." (PMID 37056774, 2023). "In the review, we discuss the expression of LAG-3 on immune cells, tumor cells, interaction with other immune checkpoints as well as the LAG-3-directed therapies." (PMID 37509517, 2023). "The primary function of LAG-3 involves the negative regulation of T-cell function, the maintenance of immune system homeostasis, and the promotion of tumor immune escape." (PMID 37575241, 2023). "Analysis of the tumour samples again found expression of the inhibitory coreceptor LAG-3, which is known to interact with MHC-II on tumour cells." (PMID 37835509, 2023). "LAG-3 and PD-1 has been observed to be co-expressed on intratumoral T cells and dual knockdown exhibit synergistical inhibition of tumor growth compared with either monotherapy." (PMID 36810034, 2023). "Increased infiltration of CD8+ T immune cells, activation of immune checkpoints, such as CD274 and LAG3, and high immune scores play a crucial role in hot tumours." (PMID 37006256, 2023). "LAG3-mediated signaling impairs the anti-tumor immune response of human T and NK cells in the TME46." (PMID 37817484, 2023).